FGF2 (fibroblast growth factor 2)
Diseases named in the same sentence as FGF2 in open-access papers (continued):
Sharing a sentence is not in itself a finding about the gene and the disease.
relapsing-remitting MS (2 papers, 2019 to 2021). "Analysis of the cerebrospinal fluid (CSF) of patients with relapsing-remitting MS showed higher levels of FGF2 expression than healthy controls and revealed that an increased concentration of FGF2 positively correlates with lesion load of disease activity." (PMID 34502405, 2021).
seminoma (2 papers, 2015 to 2019). A radiosensitive malignant germ cell tumor found in the testis (especially undescended), and extragonadal sites (anterior mediastinum and pineal gland). "Among them, GDF3, NODAL, LEFTY1 /2, GAL, DPPA3, SOX2, DNMT3B /L, DPPA5, BCAT1, FGF2, PRDM14, ZIC3 and FZD7, while seminoma markers SOX17, cKIT and PRAME were downregulated." (PMID 26226633, 2015).
synovial sarcoma (2 papers, 2010 to 2020). "The six unshared genes (CEBPB, BMP6, PTGS2, DMP1, FGF2, and H2AFV) are likely the important contributors to the ossifying phenotype seen in the metastatic synovial sarcomas." (PMID 32290096, 2020).
Takayasu arteritis (2 papers, 2019 to 2022). A rare inflammatory large-vessel vasculitis primarily affecting the aorta and its major branches, but also other large vessels, causing stenosis, occlusion, or aneurysm. "Increased serum levels of VEGF and FGF2 have earlier been reported in patients with autoimmune vascular diseases such as polyarteritis nodosa and Takayasu’s arteritis, two conditions with clinical pictures that can be confused with neoehrlichiosis." (PMID 35430702, 2022).
Tinnitus (2 papers, 2017 to 2024). Tinnitus is an auditory perception that can be described as the experience of sound, in the ear or in the head, in the absence of external acoustic stimulation. "Remarkably, the growth factors NGF, NTF3, and FGF2 are only present in the pathways associated with tinnitus." (PMID 39062188, 2024).
urothelial carcinoma (2 papers, 2017 to 2023). A malignant neoplasm derived from the transitional epithelium of the urinary tract (urinary bladder, ureter, urethra, or renal pelvis). "ROC curve analysis showed that high levels of FGF2 expression in the stroma are associated with a low potential of urothelial carcinomas to infiltrate the submucosa (p<0.0001)." (PMID 36843751, 2023).
visceral leishmaniasis (2 papers, 2014 to 2018). A severe form of leishmaniasis characterized by irregular bouts of fever, substantial weight loss, swelling of the spleen and liver, and anemia (which may be serious). "In a hamster model of visceral leishmaniasis (VL), Osorio and colleagues showed that Leishmania donovani infected macrophages displayed enhanced STAT6 and STAT3 signalling in response to the growth factors FGF2 and IGF1, further enhanced by co-stimulation with IL-4 or IL-10." (PMID 29352310, 2018).
acoustic neuroma (1 paper, 2013). A type of benign brain tumor that begins in the Schwann cells, which produce the myelin that protects the acoustic nerve - the nerve of hearing. "Although perhaps not completely relevant to HL, elevated FGF2 mRNA is thought to be involved in tumor development and progression, as was demonstrated in acoustic neuromas." (PMID 23988031, 2013).
adamantinoma (1 paper, 2016). A low grade malignant neoplasm arising from the long bones. "During progression of adamantinoma, the epithelial cells acquire expression of FGF-2, EGF, and EGFR, accompanied by a higher proliferative activity." (PMID 27630780, 2016). "The expression of fibroblast growth factor type 2 (FGF-2) and its receptor (FGFR) was present in both components of adamantinoma, but predominantly in the epithelial component." (PMID 27630780, 2016).
alcohol (1 paper, 2016). "The levels of several hematopoietic cytokines were also negatively correlated with lifetime severity of alcoholism, including IL12(p70), FGF2, fractalkine, as well as chemokine, MCP3, required for activation of immune signaling, leukocyte and monocyte response and wound healing." (PMID 27043532, 2016).
alcohol addiction (1 paper, 2023). "Nevertheless, less is known about the underlying mechanisms of epigenetic regulation of either Fgf-2 or its main receptor, Fgfr1, in the context of alcohol addiction." (PMID 36834747, 2023). "We found that Fgf-2 and its main receptor, Fgfr1, play an essential role in the development of alcohol addiction as both promoters show changes in their methylation patterns as well as their gene expression in specific brain areas." (PMID 36834747, 2023). "Furthermore, this study provides the in-silico identification of alcohol-related transcription factors in the methylation pattern of the Fgf-2 gene which may serve as potential targets for future pharmacological interventions to prevent alcohol addiction behaviors." (PMID 36834747, 2023).
alcohol use disorder (1 paper, 2025). "It is also suggested by another study of the fibroblast growth factor 2 (FGF2) and its receptor FGFR1 which are linked to alcohol consumption and other behaviors associated with alcohol use disorder." (PMID 40806293, 2025).
amnesia (1 paper, 2013). Pathologic partial or complete loss of the ability to recall past experiences ( AMNESIA, RETROGRADE) or to form new memories ( AMNESIA, ANTEROGRADE). "Along with potentially accelerating structural brakes in plasticity, it is also possible that early life stress/CORT/FGF2 exposure caused an early termination of infantile amnesia, impaired context learning, and erasure-like extinction via a CREB-mediated pathway." (PMID 23964249, 2013).
angiokeratoma (1 paper, 2020). A vascular lesion in the papillary dermis resulting from ectasia of pre-existing vessels. "Of note, FGF2, IL-7 and VEGFA explained solely a small variance fraction of phenotype, sudation disorder, and angiokeratoma, respectively." (PMID 32370284, 2020).
aortic valve disease (1 paper, 2021). "VEGF-A and FGF-2 are predominantly angiogenic markers where VEGF-A is significantly involved in calcific of aortic valve disease, while FGF-2 is involved in AS through increased matrix remodeling, proliferation, and inhibition of profibrotic markers." (PMID 33477548, 2021).
Apert syndrome (1 paper, 2025). Apert syndrome (AS) is a frequent form of acrocephalosyndactyly, a group of inherited congenital malformation disorders, characterized by craniosynostosis, midface hypoplasia, and finger and toe anomalies and/or syndactyly. "The presence of the FGF2 oncogenic variant can be explained because a group of syndromic craniosynostoses, such as Apert syndrome, has been associated with mutations in genes encoding proteins belonging to the same biological pathway, the fibroblast growth factor receptor (FGFR)." (PMID 40843798, 2025).
arterial disease (1 paper, 2022). "Concomitant arterial disease in mixed venous-arterial ulcers did not influence the levels of EGF, FGF-2, IL-1α, IL-1β, IL-6, PDGF, TGF-β1 and TNF-α in one study." (PMID 35742965, 2022).
aspergillosis (1 paper, 2019). Aspergillosis is an infection, growth, or allergic response caused by the Aspergillus fungus. "For example, treatment with FGF-2 improves antifungal drug activity in a murine model of aspergillosis." (PMID 30841504, 2019).
bone metabolism disorders (1 paper, 2025). "Therefore, the relationships between the GH/IGF-I axis, FGF-2, and VKDPs observed in children with PWS may be related to bone metabolism disorders in these patients." (PMID 41303309, 2025).
bone resorptive disease (1 paper, 2015). "Thus, endogenous FGF2 might participate in the pathogenesis of that bone resorptive disease through its direct action on osteoclasts." (PMID 25860297, 2015).
Bradycardia (1 paper, 2012). A slower than normal heart rate (in adults, slower than 60 beats per minute). "However, according to another study, the expression of this gene remains unchanged during angiogenesis caused by bradycardia, suggesting that FGF2 does not play a direct role in this process." (PMID 22827927, 2012).
brain glioblastoma (1 paper, 2015). A WHO grade IV malignant astrocytic tumor that arises from the brain, usually the cerebral hemispheres. "We investigated the mechanisms regulating FGF2 cellular localization in T98G human brain glioblastoma cells." (PMID 26056081, 2015).
breast hyperplasia (1 paper, 2025). Breast hyperplasia refers to hyperplastic proliferations of the epithelial cells in the breast parenchyma. "The expression of angiogenic factors (e.g., VEGFA, FGF2) is closely related to the occurrence and development of breast hyperplasia." (PMID 40550087, 2025).
bronchopulmonary dysplasia (1 paper, 2021). Bronchopulmonary dysplasia is a chronic respiratory disease that results from complications related to lung injury during the treatment of infant acute respiratory distress syndrome in low-birth-weight premature infants or from abnormal lung development in older infants. "Aberrant pulmonary vascular growth and remodeling are frequently seen in bronchopulmonary dysplasia, and the fibroblast growth factor (FGF)-2 and VEGF are promising targets in the treatment of respiratory disorders." (PMID 34858969, 2021).
calcific (1 paper, 2022). "FGFR ligands associated with cardiovascular calcification are FGF2, FGF21, and FGF23." (PMID 36237897, 2022). "In the calcified valve, FGF2 expression is low while FGFR1 expression is high, suggesting a possible correlation between FGFR signaling and calcific disease." (PMID 36237897, 2022).
Candidiasis (1 paper, 2019). Infection with the organism Candida. "Previous studies by our group and others have shown that Candida albicans, a common agent of candidiasis, induces FGF-2 secretion in vitro and angiogenesis in brains and kidneys during systemic infections." (PMID 30841504, 2019).
Chlamydia infection (1 paper, 2025). "In addition, Chlamydia infection is enhanced in a heparan sulfate proteoglycan (HSPG)-dependent manner via the fibroblast growth factor 2 (FGF2)-mediated signaling pathway." (PMID 40723871, 2025).
choroidal neovascularization (1 paper, 2019). An eye disorder described by the growth of new blood vessels that originate from the choroid through a break in the Bruch membrane into the sub–retinal pigment epithelium (sub-RPE) or subretinal space. "In in vivo studies conducted in mice and rats, RBM-007 was able to inhibit FGF2-induced angiogenesis, laser-induced choroidal neovascularization (CNV), and CNV with fibrosis." (PMID 31454678, 2019).
chronic pancreatitis (1 paper, 2011). A chronic inflammatory process causing damage and fibrosis of the pancreatic parenchyma. "Expression levels of TGF-β1, connective tissue growth factor, FGF-1, and FGF-2 mRNA expression levels were elevated in a transgenic mouse model of chronic pancreatitis." (PMID 24212642, 2011). "During recovery period following pancreatitis some growth factors like PDGF-A, FGF-2, VEGF and TGF-ß are maximally changed suggesting that acute pancreatitis resolved without fibrogenesis does not progress into chronic pancreatitis." (PMID 24212642, 2011).
cocaine addiction (1 paper, 2023). "Upstream non-key genes (FGF2, VEGFA, and IL1B) affect the expression of downstream genes in this pathway, while MAP2K2 regulates ERK through phosphorylation, thereby affecting cocaine addiction." (PMID 37469839, 2023).
craniosynostosis (1 paper, 2013). Craniosynostosis is defined as the premature fusion of one or more cranial sutures leading to secondary distortion of skull shape resulting in skull deformities with a variable presentation. "Overexpression of FGF2 has been implicated in craniosynostosis." (PMID 23935926, 2013).
Crouzon syndrome (1 paper, 2013). Crouzon disease is characterized by craniosynostosis and facial hypoplasia. "In addition, a study investigating the effects of FGF2 administration to Crouzon Syndrome (FGFr Autosomal Dominant Craniosynostosis Syndrome) patient derived parietal bone osteoblasts suggested an inverse relationship between FGF2 and DCN." (PMID 23935926, 2013).
cystic fibrosis (1 paper, 2022). Autosomal recessive disorder caused by pathogenic variants in the CFTR gene (cystic fibrosis transmembrane conductance regulator), which encodes a chloride and bicarbonate channel expressed in epithelial cells, and follow the diagnosis criteria. "On the contrary, activations of the UPS process could be employed as a therapeutic measure in some diseases, such as for FGF2 in AD and PD, IDE in AD, trafficking-deficient CFTR in cystic fibrosis, and trafficking-deficient pendrin in Pendred syndrome." (PMID 35774225, 2022).
demyelination (1 paper, 2011). "It is likely that this orchestration of repair promoting factors follows a strict pattern since this can also be observed in the lysolecithin model of demyelination, in particular for IGF-1, FGF-2, TGF-ß1." (PMID 21818353, 2011).
Duchenne muscular dystrophy (1 paper, 2025). Duchenne muscular dystrophy (DMD) is a neuromuscular disease characterized by rapidly progressive muscle weakness and wasting due to degeneration of skeletal, smooth and cardiac muscle. "The elevated miR-214-3p had the potential to hasten FAP fibrogenesis by adjusting the FGF2/FGFR1/TGF-β axis, which shed light on new strategies for the treatment of fibrous degeneration of Duchenne muscular dystrophy (DMD) by interfering miR-214-3p." (PMID 39759120, 2025).
ductal carcinoma in situ (1 paper, 2020). "Comparing pure ductal carcinoma in situ and in-situ component six differentially expressed genes were found, three of them (FGF2, GAS1, and SFRP1), play a role in cell invasiveness." (PMID 32050925, 2020). "We propose these three genes (FGF2, GAS1, and SFRP1) as potential biomarkers of ductal carcinoma in situ progression, suggesting that their downregulation may be involved in the transition of stationary to migrating invasive epithelial cells." (PMID 32050925, 2020).
Dysmenorrhea (1 paper, 2023). Pain during menstruation that interferes with daily activities. "In addition, the Visual Analogue Scale (VAS) score of patients with dysmenorrhea was correlated with FGF2 level in pelvic fluid (r = 0.1026, P < 0.05)." (PMID 36845134, 2023).
dysplastic nevi (1 paper, 2019). "In dysplastic nevi, moderate to high FGF2 levels were detected, whereas in common acquired nevi, contradicting data were obtained." (PMID 31167513, 2019). "In a more recent study, FGF2 was detected in 72% of non-dysplastic nevi and only in 18% of dysplastic nevi." (PMID 31167513, 2019). "Co-expression of FGF2 and FGFR1 was found in 60% of non-dysplastic nevi and in 18% of dysplastic ones." (PMID 31167513, 2019).
encephalitis (1 paper, 2013). An acute inflammatory process affecting the brain parenchyma. "The elevation of IL-12(p70), FGF-2, PDGF-BB, and TNF-α levels in the patients with encephalitis indicated clear contrast with the normal findings in those with sCJD." (PMID 24219883, 2013).
erectile dysfunction (1 paper, 2014). Persistent or recurrent inability to achieve or to maintain an erection during sexual activity. "In this study, we determined the proangiogenic paracrine effect of USCs on improving erectile dysfunction using cell therapy with USCs or USCs genetically-modified with FGF2 in a rat model of type 2 diabetic ED." (PMID 24663037, 2014). "A control group of normal rats (G1, n = 10), and four other test groups of type 2 diabetic erectile dysfunction rats: PBS as a negative control (G2, n = 10), USCs (G3, n = 15), lentivirus-FGF2 (G4, n = 15), and USCs-FGF2 (G5, n = 15)." (PMID 24663037, 2014).
Facial palsy (1 paper, 2024). Facial nerve palsy is a dysfunction of cranial nerve VII (the facial nerve) that results in inability to control facial muscles on the affected side with weakness of the muscles of facial expression and eye closure. "In particular, some authors described the use of a silicone conduit embedded with fibroblast growth factor (FGF-2) or adipose stem cells in a rat facial palsy, demonstrating the potential regenerative role of the facial nerve." (PMID 39458074, 2024).
Fibroadenoma (1 paper, 2018). A benign tumor of the breast characterized by the presence of stromal and epithelial elements. "We also observed increased levels of FGF2 and EGF in fibroadenomas (data not shown)." (PMID 30019538, 2018).
gangrene (1 paper, 2025). Death of tissue, usually in considerable mass and generally associated with loss of vascular (nutritive) supply and followed by bacterial invasion and putrefaction. "Through a systematic analysis of 12 drugs and six key genes (IGF1, IL17A, ACE, FGF2, IL6 and TLR4), we have provided a new scientific perspective on gangrene prevention in diabetic patients." (PMID 40657379, 2025).
germ cell tumor (1 paper, 2014). A benign or malignant, gonadal or extragonadal neoplasm that originates from germ cells. "Bcl6b encodes a transcription factor and downstream target of FGF2 capable of promoting germ cell tumors." (PMID 25070369, 2014).
gestational diabetes (1 paper, 2022). Carbohydrate intolerance first diagnosed during pregnancy. "It is revealed that high blood glucose concentration and gestational diabetes in obese models and inhibits the signalling of FGF2 but not of VEGF, which is significantly responsible for ex vivo angiogenesis." (PMID 36078079, 2022).
gingival enlargement (1 paper, 2024). "IL-6, TNF-α, ST2, and FGF-2 expression levels were lower in patients taking amlodipine, with and without gingival enlargement." (PMID 39204180, 2024).
hearing loss (1 paper, 2021). "However, there are many unanswered questions prior to verifying FGF2 as a useful therapeutic for hearing loss." (PMID 35002617, 2021).
hypospadias (1 paper, 2024). Hypospadias is the displacement of the urethral meatus on the ventrum of the penis. "The proteins fibulin-1, elastin, matrix metalloproteinase-1 (MMP-1), basic fibroblast growth factor (bFGF or FGF-2), and α-smooth muscle actin (α-SMA) play roles in hypospadias development." (PMID 39476852, 2024).
hypothyroidism (1 paper, 2025). Abnormally low levels of thyroid hormone. "Collectively, findings suggest that hypothyroidism disrupts the balance between pro-angiogenic factors such as VEGF and fibroblast growth factor 2 (FGF2) and anti-angiogenic mediators such as endostatin." (PMID 41158934, 2025).
hypoxia (1 paper, 2025). A decrease in the amount of oxygen in the body. "Although FGF2 is an angiogenic factor with secretion dynamics that remain unresolved, it is expressed by necroptotic microglia in hypoxia-induced retinopathy." (PMID 40591415, 2025).
inflammatory breast carcinoma (1 paper, 2012). An advanced, invasive breast adenocarcinoma characterized by the presence of distinct changes in the overlying skin. "Especially for inflammatory breast cancers it has been described that they have an angiogenic phenotype and that factors such VEGF-C, VEGF-D and FGF-2 are increased in comparison to non-inflammatory breast carcinomas." (PMID 23076721, 2012).
Interstitial cardiac fibrosis (1 paper, 2023). A type of myocardial fibrosis characterized by excessive diffuse collagen accumulation concentrated in interstitial spaces. "Augmented FGF-2 expression was noted in the hearts of spontaneously hypertensive rats, and this correlated with interstitial cardiac fibrosis." (PMID 37188903, 2023).
interstitial lung disease (1 paper, 2022). A diverse group of lung diseases that affect the lung parenchyma. "IL17, TGFβ, CTGF and FGF2 levels were higher in SSc patients with interstitial lung disease and digital ulcers, whereas IL-17A production was lower in patients with PAH." (PMID 35693738, 2022). "By univariate analysis the clinical manifestations associated to IL-17A, TGFβ, FGF2 and CTGF production by PBMCs were interstitial lung disease (ILD), PAH and DU (p<0,01)." (PMID 35693738, 2022).